TRPV4 (transient receptor potential cation channel subfamily V member 4)
Diseases named in the same sentence as TRPV4 in open-access papers (continued):
Sharing a sentence is not in itself a finding about the gene and the disease.
status epilepticus (5 papers, 2019 to 2025). Status epilepticus is defined as a continuous seizure lasting more than 30 min, or two or more seizures without full recovery of consciousness between any of them. "A recent study in mice with pilocarpine-induced status epilepticus highlights the connection between TRPV4 activation and NFκB nuclear translocation in neurons." (PMID 38521959, 2024). "Next, we explored the role of TRPV4 in the inflammation and neuronal damage post status epilepticus in pilocarpine model of temporal lobe epilepsy in mice (pilocarpine-induced status epilepticus, PISE)." (PMID 31097691, 2019). "We conclude that TRPV4-induced neuronal death is mediated at least partially by enhancing the neuroinflammatory response, and this action is involved in neuronal injury following status epilepticus." (PMID 31097691, 2019). "injection of TRPV4-specific antagonist HC-067047 markedly increased the number of surviving cells 3 d post status epilepticus in pilocarpine model of temporal lobe epilepsy in mice (pilocarpine-induced status epilepticus, PISE)." (PMID 31097691, 2019). "A study proved that the TRPV4 specific inhibitor HC067047 could block the increases in NLRP3 and caspase-1 following pilocarpine-induced status epilepticus in mice, and the experimental results are consistent with our data." (PMID 35093118, 2022).
temporal lobe epilepsy (5 papers, 2019 to 2025). A localization-related (focal) form of epilepsy characterized by recurrent seizures that arise from foci within the temporal lobe, most commonly from its mesial aspect. "Blocking transient receptor potential vanilloid 4 (TRPV4) can reduce neuronal injury in temporal lobe epilepsy (TLE) model mice." (PMID 40205503, 2025). "Herein, we examined the contribution of neuroinflammation to TRPV4-induced neurotoxicity and its involvement in the inflammation and neuronal damage in pilocarpine model of temporal lobe epilepsy in mice." (PMID 31097691, 2019). "This pattern is consistent with previous studies, such as in the temporal lobe epilepsy model, where TRPV4 inhibition ameliorated pyroptosis-related outcomes without altering expression levels." (PMID 41341920, 2025).
viral infection (5 papers, 2018 to 2025). "During herpes simplex virus type 2 (HSV-2) infection, viral glycoproteins can bind to TRPV4 channels and induce a rapid and transient rise in intracellular Ca2+ concentration, promoting viral infection." (PMID 39941149, 2025). "In fact, prior work has shown that TRPV4 can influence viral infection by inducing nuclear translocation of DEAD-Box Helicase 3 X-Linked (DDX3X), a protein that promotes nuclear viral export and translation." (PMID 35396513, 2022). "Nevertheless, future research will also need to be carried out to define the optimal therapeutic window for use of RAGE and TRPV4 inhibitors in patients with viral infection." (PMID 35396513, 2022). "This difference in viral load response suggests that TRPV4 is likely acting in multiple signaling pathways in parallel, and at least one other contributes to host response to viral infection via a distinct mechanism." (PMID 35396513, 2022). "The activation of TRPV4 by viral proteins links viral infection to the nuclear translocation of DDX3X, where it participates in the nuclear export of unspliced or partially spliced viral RNAs8." (PMID 29899501, 2018). "For example, it will also be interesting in the future to explore TRPV4's action in response to (a) other types of infectious stimuli (e.g., Gram positive organisms, viral infections such as SARS-CoV-2), (b) sex differences, and (c) transcriptional/epigenetic mechanisms." (PMID 32676078, 2020). "Therefore, we evaluated the role of TRPV4 in the mechanism of viral infection." (PMID 29899501, 2018). "Further confirmation for the role of TRPV4 in viral infection was obtained by exposing mouse embryonic fibroblast (MEF) generated from Trpv4+/+ and Trpv4−/− mice to DENV." (PMID 29899501, 2018). "The ion channel TRPV4 senses many environmental cues, but its role in virus infection is not known." (PMID 29899501, 2018).
atopic dermatitis (4 papers, 2018 to 2024). "Additionally, TRPV4 has been linked to various skin diseases, from atopic dermatitis to inflammatory conditions, highlighting its potential as a therapeutic target in such conditions." (PMID 39517820, 2024). "TRPV4 activation in macrophages inhibits NF-κB signaling, leading to the suppression of IL-1β production that is involved in the development of inflammatory diseases such as atopic dermatitis." (PMID 39517820, 2024). "We also observed a significant increase in the number of inducible NO synthase–positive/TRPV4-negative dermal macrophages in atopic dermatitis compared with healthy human skin specimens." (PMID 36645854, 2023).
brachydactyly (4 papers, 2018 to 2024). A disease characterized by the presence of brachydactyly, including syndromic and non-syndromic forms. "Two different heterozygous variants were identified in coding regions of TRPV4, the gene associated with several skeletal and neuromuscular disorders, as well as with digital arthropathy-brachydactyly." (PMID 38929227, 2024).
colon adenocarcinoma (4 papers, 2020 to 2023). "In a study of 93 patients, decreased TRPV3 and TRPV4 mRNA was found in colonic adenocarcinoma compared to normal tissue." (PMID 37240443, 2023). "The findings unveiled a novel three TRP channels-related gene signature (MCOLN1, TRPM5, and TRPV4) in colon adenocarcinoma (COAD)." (PMID 38188686, 2023). "We found that most of these mutants induced a strong gain of invasiveness of colon adenocarcinoma SW480 cells, both for TRPV4 and TRPV6." (PMID 32186440, 2020).
COVID-19 (4 papers, 2020 to 2023). A disease caused by infection with severe acute respiratory syndrome coronavirus 2. "Although studies have proposed TRPV4 in SARS-CoV-2 infection, and targeted inhibition of TRPV4 is a candidate therapeutic approach against COVID-19,47,48 our results indicate that acute exposure, but not prolonged exposure, to S-RBD leads to increased TRPV4 activity." (PMID 37452066, 2023).
demyelination (4 papers, 2018 to 2024). "As we observed here, TRPV4 expression is rapidly increased in SCs upon injury followed by nerve demyelination." (PMID 33247229, 2020). "In this study, we found that TRPV4 was increasingly expressed in a CPZ-induced demyelination mouse model and that the use of its antagonist partially prevented demyelination, glia reactivity and inflammation." (PMID 30455633, 2018). "Consequently, acutely inhibiting TRPV4 has been shown to be beneficial in multiple CNS-disease models like cuprizone-induced demyelination and SCI." (PMID 38521959, 2024). "This study suggests that inhibition of TRPV4 may protect the myelin sheath from degeneration by alleviating inflammation in the CPZ-induced demyelination model." (PMID 30455633, 2018). "In the current study, we confirmed that inhibition of TRPV4 activity with RN-1734 suppressed microglial and astrocytic activation and decreased the production of IL-1β and TNF-α in mice with CPZ-induced demyelination." (PMID 30455633, 2018). "Another possible explanation is that TRPV4 modulation alters the phenotype of homeostatic microglia but does not impact microglia in the context of cuprizone-mediated demyelination, EAE, and MS." (PMID 38069420, 2023).
fibromyalgia (4 papers, 2015 to 2023). A chronic disorder of unknown etiology characterized by pain, stiffness, and tenderness in the muscles of neck, shoulders, back, hips, arms, and legs. "Electroacupuncture inhibited the hyper-excitable of the dorsal root ganglion neurons and expression of TRPV1 and TRPV4 in the spinal cord of a murine model of fibromyalgia." (PMID 33002009, 2020). "TRPV1 and TRPV4 are believed to play a crucial role in the pathophysiology of fibromyalgia." (PMID 32630156, 2020). "Furthermore, the downregulation of TRPV4, p-p38, p-JNK, and pCREB in the peripheral nervous system and CNS may account for the therapeutic effect of acupuncture in fibromyalgia." (PMID 32630156, 2020).
Headache (4 papers, 2015 to 2023). Cephalgia, or pain sensed in various parts of the head, not confined to the area of distribution of any nerve. "Expression of TRPV4 on meningeal nociceptors was shown using application of channel activators to retrogradely-labeled trigeminal neurons in vitro, which produced currents consistent with TRPV4, and activation of this channel in the dura caused headache behavioral responses in rats." (PMID 30970581, 2019). "TRPV4 is expressed in meningeal nociceptive neurons with PAR2, and activating this channel in the dura causes headache behavioral responses, such as cephalic and extracephalic allodynia." (PMID 37175602, 2023). "Activation of TRPV4 with hypotonic solutions and 4α-PDD within the meninges produced afferent nociceptive signalling and caused headache behavioural responses in rats, which were blocked by the TRPV4 antagonist RN1734." (PMID 36986537, 2023).
meningioma (4 papers, 2021 to 2024). A generally slow growing tumor attached to the dura mater. "AQP4 and TRPV4 expression is rather associated with a response to vasogenic edema of meningiomas than with edema formation." (PMID 33538957, 2021). "We investigated AQP4/TRPV4 channel co-expression in meningiomas along with the neovascularization of tumors and associate with PTBE." (PMID 33538957, 2021). "The aim of this study was to investigate the co-expression of AQP4/TRPV4 in meningothelial cells and associate it with PTBE in meningiomas." (PMID 33538957, 2021). "In the present study, we detected the co-expression of AQP4 and TRPV4 in 35% of meningiomas, specifically grade I. This finding drove us to investigate the relationship of this co-expression with edema formation and edema extent in these tumors." (PMID 33538957, 2021). "Functional experiments would clarify the exact action of a possible cooperation of AQP4 and TRPV4 in pathogenesis of meningiomas." (PMID 33538957, 2021). "TRPV4 nuclear immunoreactivity was detected in endothelial cells of high-grade meningiomas (grade II and III)." (PMID 33538957, 2021). "Our data suggest that the microvascular density, contrary to AQP4 and/or TRPV4 expression, is strongly associated with PTBE extent in meningiomas." (PMID 33538957, 2021). "Evaluation of AQP4/TRPV4 expression in peri-meningioma (peri-tumor) tissue compared with the main tumor of edematous meningiomas revealed significantly increased expression for AQP4 (p = 0.007) but not for TRPV4 (p > 0.05) in peri-meningioma tissue." (PMID 33538957, 2021). "Thus, as AQP4 may be in fact a feedback response to vasogenic edema, the co-upregulation and presumed synergistic role of AQP4 and TRPV4 in meningiomas with larger edema could also be a response to edema." (PMID 33538957, 2021). "Fifty-eight percent of meningiomas were AQP4 immunonegative (LI < 10) and TRPV4 immunopositive (LI ≥ 10) or AQP4/TRPV4 immunonegative (LI < 10)." (PMID 33538957, 2021). "Meningioma cells demonstrated moderate to strong cytoplasmic immunoreactivity for AQP4 and TRPV4 channel expression." (PMID 33538957, 2021). "In 35% of meningiomas, AQP4/TRPV4 co-expression in ≥ 10% tumor cells (LI ≥ 10) was observed over a wide range in the tumor body but its expression in tumoral tissues nearby or to invading the meninges increased significantly." (PMID 33538957, 2021). "These are contradicting data compared with a recent evidence for cooperation of TRPV4 with AQP4 in astrocytes which results in edema formation and may support the theory that PTBE in meningiomas depends on different mechanism from that of cytotoxic edema." (PMID 33538957, 2021). "Tissue obtained from meningioma patients demonstrated AQP4/TRPV4 co-expression in both edematous and non-edematous meningiomas, although in the surrounding peri-meningioma tissue, only AQP4 was upregulated." (PMID 34616399, 2021). "Importantly, peri-meningioma tissue of edematous meningiomas demonstrated significantly increased expression for AQP4 (p = 0.007) but not for TRPV4 (p > 0.05) compared with the main tumor." (PMID 33538957, 2021). "AQP4/TRPV4 co-expression was detected in both edematous and non-edematous meningiomas." (PMID 33538957, 2021). "A proportion of edematous (76.5%) and non-edematous (66.7%) meningiomas demonstrated co-expression in ≥ 10% of tumor cells (LI ≥ 10%) of AQP4 and TRPV4 channels." (PMID 33538957, 2021). "There was a significant correlation between AQP4 and TRPV4 expression levels in benign (WHO, grade I) (Spearman rho = 0.366, p < 0.0001) but not in high-grade (WHO, grades II and III) meningiomas (p ≥ 0.05)." (PMID 33538957, 2021). "AQP4 and TRPV4 were correlated in benign (WHO, grade I) (p < 0.0001) but not in high-grade (WHO, grades II and III) meningiomas (p > 0.05)." (PMID 33538957, 2021).
meningioma (continued). "Peritumoral edema was unrelated to the expression of TRPV4 and much more neither the combination of AQP4 and TRPV4 since 76.5% of edematous and 66.7% of non-edematous meningiomas showed co-expression of AQP4 and TRPV4 channels." (PMID 33538957, 2021).
neuroblastoma (4 papers, 2021 to 2025). Neuroblastoma (NB) is the most common solid, extracranial childhood tumor. "To further explore a potential interaction between TRPV4 and ARHGEF10, we utilized MN-1 cells (a mouse motor neuron-neuroblastoma fusion cell line) to perform a series of cell-based studies of TRPV4-ARHGEF10 interactions." (PMID 41338459, 2025). "Its knockdown increases H4K8la levels and induces the transcription of the serpin family G member 1 (SERPING1) and transient receptor potential cation channel, subfamily V, member 4 (TRPV4) genes, which promotes the proliferation and migration of neuroblastoma cells." (PMID 40589733, 2025).
osteochondrodysplasia (4 papers, 2022 to 2026). A term referring to disorders characterized by abnormalities in the development of bones and cartilage. "The folded ear phenotype of Scottish Fold cats is associated with an autosomal dominant TRPV4 variant (c.1024G>T) linked to osteochondrodysplasia." (PMID 42108233, 2026). "In another recent study, a cat registered as an American Curl with curled ears was diagnosed with osteochondrodysplasia and genotypically showed one copy of TRPV4 variant." (PMID 35709088, 2022). "Moreover, we found that Scottish Fold crosses are of particular concern, as heterozygous cats also manifest Osteochondrodysplasia and the presence of TRPV4 derived allele cannot be reliably detected from the ear type if the cat has ear Curl, as also shown by others previously." (PMID 35709088, 2022). "Consequently, visual inspection for breeding selection is insufficient, highlighting the necessity of TRPV4 genotyping to prevent unintentional production of homozygous offspring with severe osteochondrodysplasia." (PMID 42087835, 2026).
Pain (4 papers, 2017 to 2025). An unpleasant sensory and emotional experience associated with actual or potential tissue damage, or described in terms of such damage. "The expression of TRPV4 in the central nervous system should be further investigated since only one study used a model of central neuropathic pain (SCI model)." (PMID 36670886, 2022). "In addition, either systematic or spinal administration of a potent TRPV4-specific antagonist GSK219 prevented the development of mechanical pain, suggesting a potential therapeutic effect of blocking TRPV4 in chronic neuropathic pain." (PMID 36701202, 2023). "Rodent studies support that some anti-cancer drugs are able to generate pain syndromes via the actions of other TRP family members including TRPV1 and TRPV4." (PMID 29084244, 2017).
peripheral nerve injury (4 papers, 2020 to 2025). Injury to a peripheral nerve. "Nociceptive stimulation-induced TRPV4 activation following peripheral nerve injury triggers Ca2+ influx, thereby enhancing DRG neuron excitability and promoting pain generation." (PMID 40809812, 2025). "Conversely, inhibition of TRPV4 ion channels reduces the hyperexcitability of peripheral fibers following peripheral nerve injury, thereby significantly improving NP-related behaviors." (PMID 40809812, 2025). "Together, our results demonstrate that microglia-expressed TRPV4 was required to mediate excitatory synaptic transmission and promote excitability in the spinal cord following peripheral nerve injury." (PMID 36701202, 2023). "Additionally, TRPV4 and sigma-1 receptors would transmit neuropathic pain from peripheral nerve injury to the spinal cord." (PMID 38393152, 2024). "Peripheral nerve injury could upregulate TRPV4 levels in myelinating SCs to induce conversion of cell types into those having demyelinating phenotypes." (PMID 33247229, 2020).
retinal degeneration (4 papers, 2015 to 2025). Degeneration of the retina. "TRPV4 mutations underpin sensorimotor neuropathies, skeletal dysplasias, retinal degeneration and ocular dysfunction while the role of TRPV4 signaling in OHT remains contentious, with evidence suggesting IOP-lowering as well as IOP-elevating effects." (PMID 39574569, 2025). "A novel TRPV4 missense mutation c.549G>C (p.E183D) was identified in the index individual from Family Q diagnosed with an axonal motor and sensory neuropathy with retinal degeneration." (PMID 25802885, 2015). "TRPV4 mutations underpin sensorimotor neuropathies, skeletal dysplasias, retinal degeneration, and ocular dysfunction, while the role of TRPV4 signaling in OHT remains contentious, with evidence suggesting both IOP-lowering and IOP-elevating effects." (PMID 40552711, 2025).
scapuloperoneal spinal muscular atrophy (4 papers, 2018 to 2024). "Charcot-Marie-Tooth disease 2C (CMT2C) and scapuloperoneal spinal muscular atrophy (SPSMA) are different clinical phenotypes of TRPV4 mutation." (PMID 37391745, 2023). "Mutations in TRPV4 can induce a number of peripheral neuropathies with implications for skeletal muscles, such as hereditary motor and sensory neuropathy type 2C mainly presenting in the pediatric age (HMSN2C), scapuloperoneal spinal muscular atrophy (SPSMA), and congenital distal SMA." (PMID 34208776, 2021).
skin cancer (4 papers, 2020 to 2022). "Another research reported that TRPV4 expression in keratinocytes of human non-melanoma skin cancer is significantly reduced, and the TRPV4 level is associated with IL-18 secretion, which indicated that TRPV4 might serve as a biomarker for the early diagnosis of skin cancer." (PMID 35558077, 2022). "In our study, we investigated the expressions of ASIC1, ASIC2, TRPV1 and TRPV4 in common skin tumors, namely SCC, BCC, NCN and MM." (PMID 34199609, 2021). "On the contrary, the expression level of TRPV4 is significantly reduced in advanced endothelial and skin cancers, suggesting that TRPV4 exhibits both oncogenic or tumour suppressor effects depend on the cancer type." (PMID 32575381, 2020). "In conclusion, ASIC1, ASIC2, TRPV1 and TRPV4 are expressed by most common skin tumors." (PMID 34199609, 2021). "ASIC1, ASIC2, TRPV1 and TRPV4 in skin tumors might be involved in tumor progression, thus being potential diagnostic and therapeutic targets." (PMID 34199609, 2021).
spondylometaphyseal dysplasia (4 papers, 2012 to 2025). Spondylometaphyseal dysplasias are a heterogeneous group of disorders associated with walking and growth disturbances that become evident during the second year of life. "Participant NE034 presented clinically with only the skeletal features of TRPV4-associated disease and received a diagnosis of spondylometaphyseal dysplasia." (PMID 38028619, 2023). "Five groups (group 8 TRPV4 group, group 12 spondylometaphyseal dysplasias, group 14 severe spondylodysplastic dysplasias, group 18 bent bones dysplasias, and group 21 chondrodysplasia punctata) described in the Nosology have not been reported yet by Chinese biomedical literature." (PMID 22913777, 2012).